TYK2 (tyrosine kinase 2)
Description:
Non-membrane spanning protein tyrosine kinase involved in numerous cytokines and interferons signaling, which regulates cell growth, development, cell migration, innate and adaptive immunity. Plays both structural and catalytic roles in numerous interleukins and interferons (IFN-alpha/beta) signaling. Associates with heterodimeric cytokine receptor complexes and activates STAT family members including STAT1, STAT3, STAT4 or STAT6. The heterodimeric cytokine receptor complexes are composed of (1) a TYK2-associated receptor chain (IFNAR1, IL12RB1, IL10RB or IL13RA1), and (2) a second receptor chain associated either with JAK1 or JAK2. In response to cytokine-binding to receptors, phosphorylates and activates receptors (IFNAR1, IL12RB1, IL10RB or IL13RA1), creating docking sites for STAT members. In turn, recruited STATs are phosphorylated by TYK2 (or JAK1/JAK2 on the second receptor chain), form homo- and heterodimers, translocate to the nucleus, and regulate cytokine/growth factor responsive genes. Negatively regulates STAT3 activity by promototing phosphorylation at a specific tyrosine that differs from the site used for signaling. Involved in the oncostatin-M-mediated signaling pathway through both type I OSM receptor complex (heterodimers composed of LIFR and IL6ST) and type II OSM receptor complex (heterodimers composed of OSMR and IL6ST).
Synonyms: JTK1; IMD35
Tractability: Small molecule: an approved drug acts on it; a structure with a bound ligand is known; a high-quality ligand is known; it has a binding pocket of medium quality; it belongs to a druggable protein family. Antibody: its Gene Ontology location is reachable by antibodies, with high confidence. PROTAC: it is named in the literature on targeted protein degradation; ubiquitination databases record sites on it; its protein half-life has been measured; a small molecule that binds it is known.
Target class: TK protein kinase group; Enzyme; Kinase; Protein Kinase; Tyrosine protein kinase JakA family
Chemical probes: CRAVACITINIB (high quality), PF-06263276, TC JL 37, Zasocitinib (high quality)
Gene: Protein-coding gene on chromosome 19 (10,350,528 to 10,380,608, reverse strand). Ensembl gene ENSG00000105397.
Subcellular location (Human Protein Atlas): Cytosol
Pathways (Reactome):
Immune System: IL-6-type cytokine receptor ligand interactions; Inactivation of CSF3 (G-CSF) signaling; Interferon alpha/beta signaling; Interleukin-10 signaling; Interleukin-12 signaling; Interleukin-20 family signaling; Interleukin-23 signaling; Interleukin-27 signaling; Interleukin-35 Signalling; Interleukin-4 and Interleukin-13 signaling; Interleukin-6 signaling; Other interleukin signaling; Regulation of IFNA/IFNB signaling; Signaling by CSF3 (G-CSF)
Disease: Evasion by RSV of host interferon responses; Potential therapeutics for SARS; SARS-CoV-2 activates/modulates innate and adaptive immune responses; Signaling by ALK fusions and activated point mutants
Signal Transduction: MAPK1 (ERK2) activation; MAPK3 (ERK1) activation
Cell-Cell communication: Activation of STAT3 by cadherin engagement
Gene Ontology:
Molecular function: growth hormone receptor binding; non-membrane spanning protein tyrosine kinase activity; protein binding; protein tyrosine kinase activity; ATP binding; protein kinase activity
Biological process: cell surface receptor signaling pathway via JAK-STAT; interleukin-10-mediated signaling pathway; interleukin-12-mediated signaling pathway; interleukin-23-mediated signaling pathway; positive regulation of protein localization to nucleus; type I interferon-mediated signaling pathway; type II interferon-mediated signaling pathway; cell differentiation; cytokine-mediated signaling pathway; growth hormone receptor signaling pathway via JAK-STAT; interleukin-5-mediated signaling pathway; intracellular signal transduction; protein phosphorylation; cell population proliferation; positive regulation of T cell proliferation
Cellular component: cytoplasm; extracellular exosome; nucleus; cytoplasmic side of plasma membrane; cytosol; extrinsic component of cytoplasmic side of plasma membrane; extrinsic component of plasma membrane; interleukin-5 receptor complex; plasma membrane; membrane
Genetic constraint (gnomAD): Loss-of-function variants: 62 observed, 122.43 expected, observed/expected ratio (o/e) 0.51, 90% interval 0.41 to 0.63. The upper end of that interval is the gene's LOEUF score, 0.63, which puts it in group 2 of 6, group 1 being the genes least tolerant of losing a copy. Missense variants: 1,376 observed, 1,599.6 expected, observed/expected ratio (o/e) 0.86, 90% interval 0.82 to 0.9. Synonymous variants: 647 observed, 655.16 expected, observed/expected ratio (o/e) 0.99, 90% interval 0.93 to 1.05.
Homologues: Orthologues: chimpanzee TYK2 (98% identical), macaque TYK2 (97% identical), pig TYK2 (83% identical), guinea pig TYK2 (79% identical), mouse Tyk2 (79% identical), rat Tyk2 (77% identical), dog TYK2 (77% identical), rabbit TYK2 (67% identical), tropical clawed frog tyk2 (59% identical), zebrafish tyk2 (50% identical). Paralogues in human: JAK1 (45% identical), JAK2 (37% identical), JAK3 (37% identical), LYN (15% identical), LCK (15% identical), HCK (14% identical), PTK2 (14% identical), BLK (13% identical), FYN (13% identical), SYK (13% identical), ABL2 (13% identical), FGR (13% identical), and 20 more.
Diseases named in the same sentence as TYK2 in open-access papers:
TYK2 is named in the same sentence as 242 diseases in open-access papers, as found by Europe PMC text mining. Sharing a sentence is not in itself a finding about the gene and the disease. The quoted sentences say what the papers report.
psoriasis (134 papers, 2013 to 2026). An autoimmune condition characterized by red, well-delineated plaques with silvery scales that are usually on the extensor surfaces and scalp. "We aim to investigate the efficacy of topically applying TYK2 inhibitor in psoriasis and to elucidate the underlying mechanisms driving the therapeutic effects of this delivery approach." (PMID 40038877, 2025). "Deucravacitinib (Sotyktu), an oral medication, allosterically inhibits tyrosine kinase 2, an enzyme that mediates signaling for key cytokines such as IL-23 and type I interferons, which are implicated in inflammatory diseases like psoriasis." (PMID 40353105, 2025). "The most significant locus (rs12720356) with a concordant direction of effect was TYK2, which encodes tyrosine kinase 2 and has been linked to an array of multiple sclerosis, psoriasis and type 1 diabetes." (PMID 41425598, 2025). "Here, we empirically determined an actual TYK2 psoriasis pathway, with genes in it that are implicated in psoriasis." (PMID 39684939, 2024). "Single nucleotide polymorphisms in the TYK2 locus are associated with a wide-range of autoimmune diseases, including psoriasis, rheumatoid arthritis, multiple sclerosis, and Crohn’s disease." (PMID 39622833, 2024). "Several of the treatments for psoriasis (for example IL23 and TYK2 inhibitors) target the products of genes linked to psoriasis." (PMID 37569685, 2023). "Tyk2 participates in the signaling of multiple regulatory and effector cytokines involved in psoriasis, and Tyk2 dysfunctional mutations are protective for psoriasis." (PMID 36834806, 2023). "In summary, using multiple analytic approaches this study found that genetically proxied TYK2 inhibition was associated with lower risk of psoriasis and its related disorders." (PMID 36842216, 2023). "JAK1, JAK2, and tyrosine kinase 2(TYK2)are key enzymes implicated in psoriasis, and JAK inhibitors reduce the transcription of pro-inflammatory cytokines by blocking the JAK-STAT pathway." (PMID 38239345, 2023). "The associations with hypothyroidism and psoriasis were confirmed in MR analysis of tissue-specific TYK2 gene expression and the associations with systemic lupus erythematosus, psoriasis, and rheumatoid arthritis were observed in colocalization analysis." (PMID 36842216, 2023). "No previous studies have ever compared the benefit and risk profile of oral inhibitors of PDE4 and TYK2 in psoriasis treatment." (PMID 37334353, 2023). "Genetic linkage studies have established a connection between dysfunctional Tyk2 mutations and protection from psoriasis." (PMID 36834806, 2023). "The TYK2 locus (rs11085727) associated with reduced risk for autoimmune conditions, e.g., psoriasis OR 0.88, p = 6.48 x10-23, lupus OR 0.84, p = 3.97 x 10−06." (PMID 35482673, 2022). "The existing literature can help explain some of the dual association between reduced risk of autoimmune conditions such as psoriasis and RA and increased risk of severe COVID-19 via TYK2." (PMID 35482673, 2022). "We used a partial loss‐of‐function variant in TYK2 (rs34536443), previously shown to protect against psoriasis and other autoimmune diseases, to evaluate the potential effect of therapeutic TYK2 inhibition on risk of lung cancer and non‐Hodgkin lymphoma." (PMID 35747941, 2022). "Here, the authors explored possible carcinogenic effects of TYK2 inhibition by genetic proxy based on a partial loss‐of‐function variant in TYK2 that provides protection against psoriasis." (PMID 35747941, 2022). "Psoriasis susceptibility genes have been identified as tyrosine kinase 2 (TYK2) and TRAF3-interacting protein 2 (TRAF3IP2)." (PMID 35409152, 2022). "The existing literature can help explain the dual association between reduced risk of autoimmune conditions such as psoriasis and RA and increased risk of severe COVID-19 via TYK2." (PMID 34642702, 2021).
psoriasis (continued). "This TYK2 signal has been previously reported to be associated with reduced risk of psoriasis, psoriatic arthropathy, type 1 diabetes, systemic lupus erythematosus and RA as well as other autoimmune inflammatory conditions." (PMID 34642702, 2021). "Deucravacitinib uniquely binds to the TYK2 regulatory domain, which allows it to target the underlying pathogenesis of psoriasis through inhibition of the intracellular component of the IL-12, IL-23, and Type I interferon pathways." (PMID 34884596, 2021). "The TYK2 locus (rs11085727) associated with reduced risk for autoimmune conditions, e.g., psoriasis OR 0.88, p=6.48 × 10−23, lupus OR 0.84, p=3.97 × 10−06." (PMID 34642702, 2021). "GWAS identified TYK2 as a psoriasis susceptibility gene in 20106, this finding has since then been replicated by others, including ourselves." (PMID 29728633, 2018). "Both IFIH1 and TYK2 are located in loci previously implicated in common variant studies of psoriasis risk." (PMID 28973304, 2017). "Since IFIH1 and TYK2 are located in known psoriasis susceptibility loci, we further scrutinized genes in all previously reported psoriasis susceptibility loci." (PMID 28973304, 2017). "Many genes (e.g., IL-12B, IL-23A, IL-23R, TRAF3IP2, and TYK2) are significantly associated with psoriasis." (PMID 29292715, 2017). "TYK2 associates with immune cytokines subunits, playing a significant role in autoimmune and inflammatory diseases, including RA, inflammatory bowel diseases, psoriasis." (PMID 40841966, 2025). "Deucravacitinib (Deu), a selective oral Tyrosine Kinase 2 (TYK2) inhibitor, shows promise in treating psoriasis but may cause systemic side effects and fail to address persistent localized thickened lesions." (PMID 39473371, 2024). "TYK2’s involvement in psoriasis is linked to Th17 responses and IFN-α signaling." (PMID 39351231, 2024). "Interestingly, individuals with a genetic polymorphism which causes loss of function of TYK2 are at lower risk of developing psoriasis." (PMID 39337637, 2024). "TYK2 is one of the JAK family genes associated with psoriasis susceptibility genes." (PMID 38239345, 2023). "In addition, the genes encoding proteins involved in the nuclear factor κB (NFκB) signaling pathway, including interleukin 12B (IL12B), IL23A, and tyrosine kinase 2 (TYK2), have also been reported as susceptibility genes for psoriasis." (PMID 37511476, 2023). "To validate rs34536443 as a surrogate for therapeutic TYK2 inhibition, we confirmed that each copy of the minor allele, representing partial TYK2 inhibition, was associated with lower risk of psoriasis (OR 0.48, 95% CI 0.39‐0.58, P = 9.01 × 10−14) and other autoimmune diseases." (PMID 35747941, 2022). "Here, we used an established partial LOF mutation in TYK2 (rs34536443), previously shown to protect against psoriasis and other autoimmune diseases, to evaluate the potential effect of therapeutic TYK2 inhibition on risk of lung cancer and non‐Hodgkin lymphoma." (PMID 35747941, 2022). "A literature search was performed to find studies thatinvestigated associations between TYK2 SNPs and autoimmunediseases (multiple sclerosis, systemic lupus erythematosus, Crohn’s disease,ulcerative colitis, psoriasis, rheumatoid arthritis, type 1 diabetes, andinflammatory bowel disease)." (PMID 33949620, 2021). "Other TYK2 variants, however, have been found to be protective in MS, RA, psoriasis and SLE." (PMID 35056105, 2021). "Large, unbiased genome wide association studies (GWAS) later found TYK2 to be associated to a range of autoimmune diseases, including rs12720356 (I684S) with Crohn’s disease [odds ratio (OR) 1.12] and psoriasis (OR 1.4), while AS was associated with an intergenic SNP near TYK2 (rs35164067, OR 1.16)." (PMID 34290741, 2021).
psoriasis (continued). "In this case study, we assessed the pleiotropy of rs12720356, a SNP located in TYK2 gene that is associated with Crohn’s disease and psoriasis, by exploring the relationships between genes (and their products) to which this SNP can be mapped using expression QTL data." (PMID 33165574, 2021). "Moreover, gene polymorphisms of IL23A, IL23R, STAT3, RUNX3, and TYK2 have also been identified as susceptibility factors for developing psoriasis." (PMID 31649667, 2019). "Furthermore, TYK2-deficient mice were more resistant to several Th1 and Th17 cells autoimmune disorders, including imiquimod-induced psoriasis-like dermatitis." (PMID 31649667, 2019). "GWAS have consistently implicated TYK2 in psoriasis susceptibility." (PMID 29728633, 2018). "Additionally, the rs34536443 SNP in TYK2 was associated with psoriasis susceptibility." (PMID 37569685, 2023). "TYK2 inhibition provided dual modulation of IL-23 and type I interferon pathways and showed emerging utility in psoriasis or PsA coexisting with CLE or SLE." (PMID 41596733, 2026). "Additional complexity arises from the variable clinical expression of lupus (skin-limited SCLE/DLE versus multi-organ SLE), the spectrum of ANA/ENA serologies, and the expanding use of newer agents such as IL-23 and TYK2 inhibitors in routine psoriasis care." (PMID 41596733, 2026). "The only small-molecule drug approved by the FDA in 2022 for the treatment of psoriasis in adults is deucravacitinib, which inhibits a tyrosine kinase 2 (TYK2) mediating IL-23, IL-12, and IFN type I signaling." (PMID 41481132, 2026). "Currently, Deucravacitinib, as the first approved selective TYK2 inhibitor, has been used to treat psoriasis." (PMID 40841966, 2025). "Deucravacitinib, a selective oral tyrosine kinase 2 (TYK2) inhibitor, has demonstrated strong efficacy in the treatment of moderate-to-severe psoriasis." (PMID 40095854, 2025). "For instance, the identification of crucial cytokines and molecules involved in the progression of psoriasis eventually led to the development of IL-17 inhibitors, TYK2 inhibitors, and IL-36 inhibitors, among others." (PMID 39846685, 2025). "Deucravacitinib is an allosteric, selective tyrosine kinase 2 (TYK2) inhibitor that has demonstrated significant efficacy in the treatment of psoriasis." (PMID 40095888, 2025). "To assess the topical efficacy of the selective TYK2 inhibitor on psoriasis, we employed a preclinical mouse model induced by IMQ cream." (PMID 40038877, 2025). "This is an important distinction, as newer agents, such as inhibitors of tyrosine kinase 2 of the Janus kinase family, can be efficacious in the treatment of psoriasis." (PMID 40678003, 2025). "Deucravacitinib, an oral, selective, allosteric tyrosine kinase 2 inhibitor, is approved in Japan for adult patients with plaque, generalized pustular, or erythrodermic psoriasis." (PMID 39641509, 2025). "Beyond its role in psoriasis, TYK2 mediates signaling for a broader range of cytokines involved in innate and adaptive immune responses, such as IL-6, IL-10, and IL-27, underscoring its potential relevance in various immune-mediated diseases." (PMID 40095888, 2025). "The development of selective tyrosine kinase 2 (TYK2) inhibitors marks a significant advancement in the treatment of immune-mediated diseases, particularly psoriasis." (PMID 40095888, 2025). "In this study, comprehensive bioinformatics analysis was performed on the expression profiles of tissue samples from patients with psoriasis in the clinical trial of TYK2/JAK1 inhibitor treatment (NCT02310750)." (PMID 40560938, 2025). "Deucravacitinib, the first oral selective allosteric TYK2 inhibitor approved for psoriasis treatment, also shows potential for addressing other immune-mediated diseases." (PMID 40095888, 2025). "Since Bristol–Myers Squibb released deucravacitinib, the world’s first oral TYK2 inhibitor for psoriasis, many ‘big pharms’ have taken notice of a target that was once thought to be ‘un-druggable’!" (PMID 39861704, 2025).